UBAC1 (UBA domain containing 1)
Description:
Non-catalytic component of the KPC complex, a E3 ubiquitin-protein ligase complex that mediates polyubiquitination of target proteins, such as CDKN1B and NFKB1. The KPC complex catalyzes polyubiquitination and proteasome-mediated degradation of CDKN1B during G1 phase of the cell cycle. The KPC complex also acts as a key regulator of the NF-kappa-B signaling by promoting maturation of the NFKB1 component of NF-kappa-B by catalyzing ubiquitination of the NFKB1 p105 precursor. Within the KPC complex, UBAC1 acts as an adapter that promotes the transfer of target proteins that have been polyubiquitinated by RNF123/KPC1 to the 26S proteasome.
Synonyms: GBDR1; KPC2; UBADC1
Tractability: Antibody: its Gene Ontology location is reachable by antibodies, with high confidence. PROTAC: ubiquitination databases record sites on it; its protein half-life has been measured.
Gene: Protein-coding gene on chromosome 9 (135,932,403 to 135,961,387, reverse strand). Ensembl gene ENSG00000130560.
Subcellular location: Cytoplasm
Subcellular location (Human Protein Atlas): Cytosol; Plasma membrane; Golgi apparatus
Pathways (Reactome):
Immune System: Antigen processing: Ubiquitination & Proteasome degradation
Gene Ontology:
Molecular function: polyubiquitin modification-dependent protein binding; proteasome binding; protein binding
Biological process: protein maturation; protein ubiquitination; modification-dependent protein catabolic process; regulation of cell cycle
Cellular component: cytoplasm; cytosol; extracellular exosome; ubiquitin ligase complex
Genetic constraint (gnomAD): Loss-of-function variants: 26 observed, 41.74 expected, observed/expected ratio (o/e) 0.62, 90% interval 0.46 to 0.86. The upper end of that interval is the gene's LOEUF score, 0.86, which puts it in group 3 of 6, group 1 being the genes least tolerant of losing a copy. Missense variants: 517 observed, 529.49 expected, observed/expected ratio (o/e) 0.98, 90% interval 0.91 to 1.05. Synonymous variants: 221 observed, 209.77 expected, observed/expected ratio (o/e) 1.05, 90% interval 0.94 to 1.18.
Homologues: Orthologues: chimpanzee UBAC1 (99% identical), dog UBAC1 (93% identical), macaque UBAC1 (91% identical), mouse Ubac1 (90% identical), rat Ubac1 (90% identical), guinea pig UBAC1 (89% identical), pig UBAC1 (79% identical), zebrafish ubac1 (78% identical), tropical clawed frog ubac1 (74% identical). Paralogues in human: TNRC6C (28% identical), TNRC6B (23% identical), TNRC6A (23% identical), UBXN4 (11% identical), UBXN1 (8% identical).
Diseases named in the same sentence as UBAC1 in open-access papers:
UBAC1 is named in the same sentence as 11 diseases in open-access papers, as found by Europe PMC text mining. Sharing a sentence is not in itself a finding about the gene and the disease. The quoted sentences say what the papers report.
lung carcinoma (1 paper, 2022). "Compared with the healthy people, in the plasma of lung cancer patients, only the expression of KLHL3 was continuously downregulated, while NEDD4 and UBAC1 were increased." (PMID 35313857, 2022).
psoriasis (1 paper, 2021). An autoimmune condition characterized by red, well-delineated plaques with silvery scales that are usually on the extensor surfaces and scalp. "The pathogenesis of psoriasis may involve the dysfunction of indoleamine 2,3-dioxygenase 2 or of UBA domain containing 1-mediated regulation of CARD14/CARMA2sh." (PMID 33804147, 2021).
tumor (2 papers, 2022 to 2024). "Since different tumor suppressors and oncogenes are controlled by the Ub- and proteosome-mediated degradation, the CSN7A, UBAC1, PSMD9, and RNF40 may play important roles in the pathogenesis of the KIRC." (PMID 36180558, 2022).
UBAC1 also shares sentences with these, for which no sentence is quoted: infection (5 papers); COVID-19 (2); nosocomial infection (2); biliary tract infection (1); cancer (1); Klebsiella pneumonia (1); pneumonia (1); thymoma (1).